HNF4A (hepatocyte nuclear factor 4 alpha)
Diseases named in the same sentence as HNF4A in open-access papers (continued):
Sharing a sentence is not in itself a finding about the gene and the disease.
lung adenocarcinoma (continued). "HNF4α expression and SMARCA4 loss were thought to be features of non-terminal respiratory unit (TRU)-type lung adenocarcinomas, but their relationships remained unclear." (PMID 38710944, 2025). "We previously reported that HNF4α was not a significant prognostic factor in lung adenocarcinomas at any stage, but confirmed that the expression of HNF4α and a solid morphology were independent poor prognostic factors in advanced stage samples." (PMID 38710944, 2025). "Furthermore, approximately half of the cases harbored EGFR mutations (3/7, 43%), suggesting that the double-positive cases for HNF4α and TTF-1 were derived from TRU-type lung adenocarcinomas." (PMID 38710944, 2025). "This hypothesis was validated in cells overexpressing and knocking down HNF4A, and the results showed that HNF significantly promoted the ferroptosis of lung adenocarcinoma cells." (PMID 37180584, 2023). "Based on The Cancer Genome Atlas data of 456 primary lung adenocarcinomas (mostly Caucasian cases), the frequency of KRAS mutations was not significantly higher in HNF4A-high cases (35.9%, 42/117 cases) than in HNF4A-low cases (29.5%, 100/339 cases) (p = 0.121) (Online resource 9)." (PMID 38710944, 2025). "All four cell lines may be regarded as representatives of non-mucinous HNF4α-positive lung adenocarcinomas with grade 3 morphology, but their immunohistochemical and genetic features varied." (PMID 38710944, 2025). "Our previous report revealed that the main group of non-TRU-type lung adenocarcinomas were hepatocyte nuclear factor 4α (HNF4α)-positive adenocarcinomas with gastrointestinal features that frequently harbored KRAS mutations and TTF-1 inactivating mutations/hypermethylation." (PMID 38710944, 2025). "None of the HNF4α-positive lung adenocarcinomas showed hepatoid differentiation." (PMID 38710944, 2025). "It has not yet been shown how HNF4A affects POR expression or ferroptosis in lung adenocarcinoma." (PMID 37180584, 2023). "Therefore, bronchiolar metaplastic lesions strongly expressing HNF4α are considered precancerous lesions of non-TRU lung adenocarcinomas." (PMID 33462379, 2021). "A total of 6 lung adenocarcinoma samples from the 3 patients with double primary lung adenocarcinomas were all positive for TTF-1 and negative for HNF4α." (PMID 38710944, 2025).
pancreatic ductal adenocarcinoma (5 papers, 2019 to 2026). An infiltrating adenocarcinoma that arises from the epithelial cells of the pancreas. "In contrast, in pancreatic ductal adenocarcinoma, invasive mucinous adenocarcinoma, and other lineage-defined epithelial tumors, HNF4α can also participate in transcriptional programs that sustain malignant identity, metabolic adaptation, and therapeutic resistance." (PMID 41925866, 2026).
prediabetes (5 papers, 2014 to 2023). "The present study is the first to report an association between the HNF4A gene variant (rs4812829) with prediabetes, suggesting that the heterozygous genotype (GA) is protective of prediabetes risk in Saudi Arabian adults." (PMID 36980809, 2023). "We performed a case-control study to identify the effect of rs1884613 of HNF-4α gene on prediabetes and T2D susceptibility in Han Chinese population." (PMID 25400315, 2014). "In summary, we found significant associations between prediabetes risk and five variants closely related to the FTO, HNF4A, WFS1, DUSP9, and ZFAND6 genes (rs4812829, rs1801214, rs5945326, rs11642841, and rs11634397) among Saudi Arabian adults." (PMID 36980809, 2023). "Furthermore, heterozygous GA of rs4812829 (HNF4A), rs5945326 (DUSP9), and rs11634397 (ZFAND6), along with heterozygous TC of rs1801214 (WFS1), were associated with a decreased risk for prediabetes." (PMID 36980809, 2023). "In conclusion, our results suggest that rs1884613 of HNF-4α is associated with prediabetes in Han Chinese population, whereas this polymorphism may not play an important role in the risk of T2D according to our case-control study and the updated meta-analysis." (PMID 25400315, 2014). "The lack of enrichment of prediabetes in individuals with HNF1A and HNF4A variants in unselected cohort suggest that these individuals do not have enrichment of milder subclinical disease." (PMID 36257325, 2022).
cervical cancer (4 papers, 2018 to 2025). A primary or metastatic malignant neoplasm involving the cervix. "In this study, both immunohistochemistry and western blotting revealed that the expression of HNF4A was downregulated in cervical cancer." (PMID 35132353, 2022). "The analysis in the GEO database suggested that the mRNA levels of HNF4A were also low in cervical cancer tissue." (PMID 35132353, 2022). "The results both revealed that the expression levels of HNF4A protein were low in cervical cancer tissue." (PMID 35132353, 2022). "Altogether, our findings firstly described that HNF4A was downregulated in cervical cancer specimens and HNF4A inhibited tumor formation and proliferation of cervical cancer cells through suppressing the activity of the Wnt/β-catenin pathway." (PMID 35132353, 2022). "Further, MTT and cell counting assays suggested that HNF4A inhibited the proliferation and viability of cervical cancer cells in vitro." (PMID 35132353, 2022). "In the present study, IHC and western blotting were used to detect the expression level of HNF4A in cervical cancer." (PMID 35132353, 2022). "Altogether, our data demonstrated that HNF4A inhibited tumor formation and proliferation of cervical cancer cells through suppressing the activity of the Wnt/β-catenin pathway." (PMID 35132353, 2022). "Functional studies illustrated that HNF4A also inhibited the proliferation and viability of cervical cancer cells in vitro." (PMID 35132353, 2022). "Ectopic expression of HNF4A inhibited tumor formation and proliferation of cervical cancer cells both in vivo and in vitro." (PMID 35132353, 2022). "In the present study, we demonstrated that HNF4A was downregulated in cervical cancers." (PMID 35132353, 2022). "This is the first report that describes the expression of HNF4A in cervical cancer." (PMID 35132353, 2022). "Collectively, these data demonstrated that HNF4A could inhibit tumor formation and the proliferation of cervical cancer cells through inducing cell cycle arrest from the G0/G1 phase to S phase." (PMID 35132353, 2022). "Unfortunately, we did not collect enough cervical cancer specimens to measure the mRNA levels of HNF4A." (PMID 35132353, 2022).
colon adenocarcinoma (4 papers, 2020 to 2025). "The highest HNF4α expression was observed in colon adenocarcinoma (Colon AC) and rectal adenocarcinoma (Rectal AC) relative to the other types of solid cancers, including HCC." (PMID 40277924, 2025). "(E) Comparison of expression levels of CREB1 and HNF4A between native and tumor tissues in colon adenocarcinoma (COAD) and rectum adenocarcinoma (READ) tumors." (PMID 39320349, 2024). "By analyzing the GEIPA-COAD (colon adenocarcinoma) and READ (rectum adenocarcinoma) database, expression levels of CREB1 and HNF4A were found to be significantly higher in colon and rectum cancer samples than those of normal tissues." (PMID 39320349, 2024). "In the case of colon adenocarcinoma, the CDX family TFs and HNF4A, enriched in the gained peaks, have previously been shown to bind enhancer regions and maintain chromatin accessibility." (PMID 34090364, 2021).
coronary artery disease (4 papers, 2011 to 2022). "Additionally, some studies have assessed the impact of HNF4A gene variations on preventing and treating coronary artery disease complications." (PMID 36360783, 2022).
depression (4 papers, 2015 to 2021). "HNF4A was also an interesting candidate from this study, being associated with glucose and lipid metabolism as well as with inflammation-related depression and antidepressant treatment." (PMID 33824279, 2021). "Thus, Hnf4a may have critical effects in monoamine deficiency and impaired lipid metabolism, coagulation, hormonal activity, and immunological functions in depression." (PMID 25774879, 2015). "HNF4a can in turn modulate both mRNA and the protein expression levels in the brain where it plays a role in depression and physiological homeostasis." (PMID 32545722, 2020). "While HNF4A has never before been associated specifically with ASD, it has been reported to be involved in Parkinson's disease and major depressive disorder as well as in regulation of circadian rhythm." (PMID 33281715, 2020).
embryonal carcinoma (4 papers, 2009 to 2023). A non-seminomatous malignant germ cell tumor characterized by the presence of large germ cells with abundant cytoplasm resembling epithelial cells, geographic necrosis, high mitotic activity, and pseudoglandular and pseudopapillary structures formation. "HNF4A overexpression in embryonal carcinoma cells causes the formation of tight junctions in a dose-dependent manner." (PMID 19216786, 2009). "HNF4α triggered formation of the functional TJPs occludin and claudin-6/7 and the establishment of polarized epithelial morphology in F9 embryonal carcinoma cells." (PMID 34819492, 2021). "Ectopic expression of HNF4α can inhibit cell proliferation in rodent embryonal carcinoma cells, immortalized lung endothelial cells, pancreatic β-cells, and HEK293 human embryonic kidney cells." (PMID 31695151, 2020). "Previously, induction of CDKN1A expression is also demonstrated in F9 murine embryonal carcinoma cells and HEK293 human embryonic kidney cells upon transient HNF4α transfection." (PMID 31695151, 2020).
fibrosis (4 papers, 2011 to 2024). the formation of excess fibrous connective tissue in an organ or tissue in a reparative or reactive process. "For example, activation of AMPK inhibits cardiac fibrosis through hepatocyte nuclear factor 4 alpha (HNF-4α)-TGF-β1 signaling." (PMID 35602095, 2022). "Rat livers exposed to Ad-PPARγ showed significantly less fibrosis than did controls, and overexpression of HNF4α alleviated hepatic fibrosis in rats with bile duct ligation." (PMID 22190905, 2011).
gastric tumors (4 papers, 2021 to 2025). "Furthermore, new potential diagnostic markers, such as hepatocyte nuclear factor 4a (HNF4a), for the differentiation between primary gastric tumors and metastatic breast carcinoma are also under study." (PMID 40777117, 2025).
gout (4 papers, 2018 to 2022). A condition characterized by painful swelling of the joints, which is caused by deposition of urate crystals. "Additionally, HNF4A can also control gene expression in pancreatic islets, potentially further associating with uric acid and gout by affecting insulin secretion." (PMID 35813212, 2022). "A C-MAF BZIP transcription factor-encoding (C-MAF) SNP (rs889472) might also be associated with gout susceptibility by affecting uric acid metabolism, and part of the mechanism could be related to regulation of the transcription factor HNF4A." (PMID 35813212, 2022). "Among other results, this study highlighted genetic correlations of urate with gout and various metabolic traits; tissue enrichment signals in kidney and liver; and genetic signals at the master regulators for kidney and liver development HNF1A and HNF4A." (PMID 33587031, 2021).
Hepatitis (4 papers, 2016 to 2022). Inflammation of the liver. "Meanwhile, we observed that in hepatitis-related HCC, patients with higher expression of BCL2L1, EGFR, ESR1, HNF4A, MAPK8, and PTEN, and lower expression of HDAC1 had a better clinical prognosis." (PMID 36133813, 2022). "Furthermore, a study related to viral hepatitis suggested that knocking down Hnf4α markedly inhibited HBV RNA transcripts and respective DNA replication intermediates, which played a key role in delaying the progression of HBV-induced hepatitis." (PMID 36242914, 2022).
Hypercholesterolemia (4 papers, 2013 to 2024). An increased concentration of cholesterol in the blood. "Notably, in a patient with drug-resistant hypercholesterolemia, serum PCSK9 concentrations surged by 15-fold, coinciding with the detection of HNF4-α overexpression, indicating that HNF4-α might also play a role in PCSK9 regulation." (PMID 39139638, 2024).
hyperlipidemia (4 papers, 2022 to 2024). "Partial deficiency of HNF4α and/or GR due to genetic polymorphism and/or metabolic stresses is thus likely a key mechanism of the loss of resistance to hepatosteatosis and hyperlipidemia during HFHS intake." (PMID 35614477, 2022). "Taken together, data in this study strongly suggest that partial HNF4α deficiency may be a key driver of not only NAFLD but also hyperlipidemia and CAD risk during HFHS intake." (PMID 35614477, 2022). "The present study suggests a novel key role of hepatic HNF4α in preventing not only the fatty liver but also hyperlipidemia, partly via inhibiting the induction of the key lipogenic enzyme ACC and the master lipogenic factor SREBP-1C." (PMID 35614477, 2022). "The present study aimed to elucidate the role of down-regulation of HNF4α and GR in fatty liver and hyperlipidemia." (PMID 35614477, 2022). "The identification of partial deficiency of HNF4α and GR as potential key drivers of NAFLD and hyperlipidemia may help develop novel pharmaceutical and dietary interventions for HFHS-induced NAFLD and CAD." (PMID 35614477, 2022). "In contrast to the hyperlipidemia in the HNF4α HET mice, induction of the lipogenic genes Acc and Acly as well as down-regulation of genes important for hepatic catabolism and efflux of lipids appear to be responsible for hepatic lipid accumulation and hypolipidemia in the HFHS-fed HNF4α KO mice." (PMID 35614477, 2022). "However, the marked hypolipidemia in chow-fed adult HNF4α KO mice sharply contrasts with the hyperlipidemia in patients and animal models with NAFLD/non-alcoholic steatohepatitis (NASH) in which HNF4α is partially lost, a condition that may be better mimicked in mice with hetero-deficiency of HNF4α." (PMID 35614477, 2022).
hyperuricemia (4 papers, 2019 to 2025). An abnormally high level of uric acid. "We identified 17 proteins playing significant roles in this process, with enrichment analysis revealing that abnormalities in HNF4α leading to beta-cell impairment in the pancreas are critical in the onset of AF driven by hyperuricemia." (PMID 40469443, 2025). "Mediation Mendelian randomization analysis suggested that hyperuricemia may promote the development of atrial fibrillation (AF) through 17 plasma proteins, includeing hepatocyte nuclear factor 4-alpha (HNF4α), identified as key mediators." (PMID 40469443, 2025). "Hyperuricemia has a strong genetic component (40%–70%): related genes include SNPs in SLC22A12, ABCG2, HNF1A, and HNF4A." (PMID 41195208, 2025).
Lipid Metabolism Disorder (4 papers, 2016 to 2023). "Deficiency of HNF4α leads to lipid metabolic disorders and severe liver steatosis." (PMID 35459739, 2022). "In addition, activation of HNF-4α leads to the development of a gluconeogenesis and lipid metabolism disorder through miR122." (PMID 27011261, 2016).
liver dysfunction (4 papers, 2018 to 2023). "In addition to alterations to pancreatic activities, MODY patients with HNF4A mutations also display liver dysfunction as indicated by reduced apolipoprotein levels and altered lipid metabolism." (PMID 32998360, 2020). "Several studies showed that loss of HNF4A function is associated with liver dysfunction." (PMID 33260590, 2020). "In a study on liver tissue from patients at different stages of decompensation, HNF-4α expression was downregulated and correlated with liver dysfunction, fibrosis stage, and prognostically relevant serum parameters bilirubin, albumin, and prothrombin time." (PMID 36652164, 2023). "Indeed, when analyzing HNF4A expression in liver tissue from patients at different stages of decompensated liver function, a correlation was found between HNF4A levels and the extent of liver dysfunction, stage of fibrosis, and serum levels of total bilirubin." (PMID 32998360, 2020). "Although other clinical variations such as liver dysfunction have been associated with HNF4A mutations, hearing impairment has not previously been associated." (PMID 30005691, 2018).
mucinous lung adenocarcinoma (4 papers, 2021 to 2025). "Moreover, HNF-4α is reported as part of the signature genes of invasive lung mucinous adenocarcinoma, together with FOXA3, SPDEF and mucins, such as MUC5AC, MUC5B, and MUC3." (PMID 36674438, 2023). "However, the frequency of HNF4α expression in adenocarcinomas other than IMA is not well recognized, especially in non-mucinous lung adenocarcinomas." (PMID 38710944, 2025).
Parkinson disease (4 papers, 2018 to 2023). A progressive degenerative disorder of the central nervous system characterized by loss of dopamine producing neurons in the substantia nigra and the presence of Lewy bodies in the substantia nigra and locus coeruleus. "PTBP1 (down), in parallel with HNF4A (up), was identified as the most significant blood biomarkers in Parkinson’s Disease through transcriptomic and network-based meta-analysis." (PMID 29936497, 2018).
renal carcinoma (4 papers, 2017 to 2024). A carcinoma arising from the epithelium of the renal parenchyma or the renal pelvis.
Renal cyst (4 papers, 2009 to 2025). A fluid filled sac in the kidney. "Consistent with our previous results, hepatocyte nuclear factor family members HNF1α (z-score = −7.3) and HNF4α (z-score = −5), which regulate glucose homeostasis and tissue-specific gene expression, were again predicted to be highly inhibited and both were indeed downregulated in renal cysts." (PMID 39000280, 2024).
viral hepatitis (4 papers, 2022 to 2024). An acute or chronic inflammation of the liver parenchyma caused by viruses. "Network 2 contained 430 DMRs and was observed in viral hepatitis and HCC populations with three potential hub genes (FABP1, SGK2, and HNF4A)." (PMID 38302914, 2024). "Network 2 was observed in viral hepatitis and HCC, with three potential hub genes: fatty acid binding protein 1 (FABP1), serum/glucocorticoid regulated kinase 2 (SGK2), and hepatocyte nuclear factor 4 α (HNF4A)." (PMID 38302914, 2024). "Decreased methylation levels of HNF4A in HCC were similar to those of normal levels, which may be related to carcinogenesis in cases of advanced hepatitis, viral hepatitis, and chronic alcoholism." (PMID 35655171, 2022).
alcoholic steatohepatitis (3 papers, 2016 to 2023). "Both hepatocyte nuclear factor 4α (HNF4α) and CES1 were markedly reduced in patients with alcoholic steatohepatitis." (PMID 27075303, 2016).
Cachexia (3 papers, 2010 to 2025). Severe weight loss, wasting of muscle, loss of appetite, and general debility related to a chronic disease. "We observed moderately higher mRNA levels of HNF4A in the adipose tissue of weight-stable as compared with that in cachectic patients, which suggests that HNF4 could be a regulator of adhesion molecule gene expression in cachexia." (PMID 20407445, 2010).